CINP (cyclin dependent kinase 2 interacting protein)
Description:
Component of the DNA replication complex, which interacts with two kinases, CDK2 and CDC7, thereby providing a functional and physical link between CDK2 and CDC7 during firing of the origins of replication. Regulates ATR-mediated checkpoint signaling in response to DNA damage. Part of the 55LCC heterohexameric ATPase complex which is chromatin-associated and promotes replisome proteostasis to maintain replication fork progression and genome stability. Required for replication fork progression, sister chromatid cohesion, and chromosome stability. The ATPase activity is specifically enhanced by replication fork DNA and is coupled to cysteine protease-dependent cleavage of replisome substrates in response to replication fork damage. Uses ATPase activity to process replisome substrates in S-phase, facilitating their proteolytic turnover from chromatin to ensure DNA replication and mitotic fidelity. As part of 55LCC complex, also involved in the cytoplasmic maturation steps of pre-60S ribosomal particles by promoting the release of shuttling protein RSL24D1/RLP24 from the pre-ribosomal particles.
Synonyms: MGC849
Tractability: PROTAC: ubiquitination databases record sites on it.
Gene: Protein-coding gene on chromosome 14 (102,341,102 to 102,362,916, reverse strand). Ensembl gene ENSG00000100865.
Subcellular location: Nucleus
Gene Ontology:
Molecular function: preribosome binding; protein binding
Biological process: DNA replication; regulation of ribosome biogenesis; ribosomal large subunit biogenesis
Cellular component: ATPase complex; nucleus
Genetic constraint (gnomAD): Loss-of-function variants: 10 observed, 21.83 expected, observed/expected ratio (o/e) 0.46, 90% interval 0.28 to 0.78. The upper end of that interval is the gene's LOEUF score, 0.78, which puts it in group 3 of 6, group 1 being the genes least tolerant of losing a copy. Missense variants: 210 observed, 256.29 expected, observed/expected ratio (o/e) 0.82, 90% interval 0.73 to 0.92. Synonymous variants: 108 observed, 104.75 expected, observed/expected ratio (o/e) 1.03, 90% interval 0.88 to 1.21.
Homologues: Orthologues: chimpanzee CINP (98% identical), macaque CINP (96% identical), rabbit CINP (85% identical), guinea pig CINP (80% identical), pig CINP (78% identical), rat Cinp (78% identical), mouse Cinp (78% identical), dog CINP (77% identical), tropical clawed frog cinp (50% identical), zebrafish cinp (47% identical), Drosophila melanogaster CG34174 (21% identical).
Diseases named in the same sentence as CINP in open-access papers:
CINP is named in the same sentence as 16 diseases in open-access papers, as found by Europe PMC text mining. Sharing a sentence is not in itself a finding about the gene and the disease. The quoted sentences say what the papers report.
bladder cancer (1 paper, 2022). "CINP was established as a cofactor of KLF5 crucial for tumor growth in the bladder cancer and HeLa cell lines." (PMID 36591491, 2022).
COVID-19 (1 paper, 2022). A disease caused by infection with severe acute respiratory syndrome coronavirus 2. "To delve into the molecular underpinnings of RBC shape changes in COVID-19 and the reversal of such phenomena upon incubation with healthy control plasma, we perform multiomics analyses, including proteomics and metabolomics, of the four sample groups (CinC, PinP, PinC, and CinP)." (PMID 36537079, 2022).
epilepsy (1 paper, 2024). A brain disorder characterized by episodes of abnormally increased neuronal discharge resulting in transient episodes of sensory or motor neurological dysfunction, or psychic dysfunction. "In family HOU2437 with reported 1st-degree cousin parents, the pathogenic variant in CINP (HGNC:23789) was initially reported in both siblings with phenotypes of DD, ID, microcephaly, and epilepsy." (PMID 38622594, 2024).
neuroblastoma (1 paper, 2025). Neuroblastoma (NB) is the most common solid, extracranial childhood tumor. "CINP may also affect children diagnosed with neuroblastoma undergoing infusions of dinutuximab, an antibody targeting the disialoganglioside GD2, which is highly expressed in neuroblastoma cells." (PMID 39941827, 2025).
cancer (1 paper, 2024). A tumor composed of atypical neoplastic, often pleomorphic cells that invade other tissues. "Additionally, SPATA5, SPATA5L1, C1orf109, and CINP showed co-dependency in the Cancer Dependency Map19." (PMID 38554706, 2024).
cardiovascular diseases (1 paper, 2022). "In the dilated stage, TMEM205, ADIRF, C6H4orf48, NGRN, PROSER1, ERICH2, and CINP were not previously linked to cardiovascular diseases." (PMID 35625658, 2022).
CINP also shares sentences with these, for which no sentence is quoted: bladder urothelial carcinoma (1 paper); cervical squamous cell carcinoma (1); endocervical adenocarcinoma (1); glioma (1); kidney chromophobe carcinoma (1); lung adenocarcinoma (1); mesothelioma (1); microcephaly (1); pancreatic adenocarcinoma (1); tumor (1).